BRPF3 (bromodomain and PHD finger containing 3)
Description:
Scaffold subunit of various histone acetyltransferase (HAT) complexes, such as the MOZ/MORF and HBO1 complexes, which have a histone H3 acetyltransferase activity. Plays a role in DNA replication initiation by directing KAT7/HBO1 specificity towards histone H3 'Lys-14' acetylation (H3K14ac), thereby facilitating the activation of replication origins. Component of the MOZ/MORF complex which has a histone H3 acetyltransferase activity.
Synonyms: KIAA1286
Tractability: Small molecule: a high-quality ligand is known. Antibody: its Gene Ontology location is reachable by antibodies, with high confidence. PROTAC: its protein half-life has been measured; a small molecule that binds it is known.
Target class: Epigenetic regulator; Bromodomain; Reader
Chemical probes: NI-42, NI-57 (high quality), OF-1 (high quality)
Gene: Protein-coding gene on chromosome 6 (36,196,006 to 36,232,790, forward strand). Ensembl gene ENSG00000096070.
Subcellular location: Nucleus
Subcellular location (Human Protein Atlas): Nucleoplasm; Mitochondria
Pathways (Reactome):
Chromatin organization: HATs acetylate histones
Hemostasis: Platelet degranulation
Gene Ontology:
Molecular function: histone H3K14 acetyltransferase activity; histone H4K12 acetyltransferase activity; histone H4K5 acetyltransferase activity; histone H4K8 acetyltransferase activity; protein binding; histone reader activity
Biological process: positive regulation of DNA replication; regulation of developmental process; regulation of hemopoiesis; chromatin organization; chromatin remodeling
Cellular component: histone acetyltransferase complex; MOZ/MORF histone acetyltransferase complex; nucleus; cytosol; extracellular region
Genetic constraint (gnomAD): Loss-of-function variants: 18 observed, 104.12 expected, observed/expected ratio (o/e) 0.17, 90% interval 0.12 to 0.26. The upper end of that interval is the gene's LOEUF score, 0.26, which puts it in group 1 of 6, group 1 being the genes least tolerant of losing a copy. Missense variants: 1,147 observed, 1,623.1 expected, observed/expected ratio (o/e) 0.71, 90% interval 0.67 to 0.74. Synonymous variants: 570 observed, 640.26 expected, observed/expected ratio (o/e) 0.89, 90% interval 0.83 to 0.95.
Homologues: Orthologues: chimpanzee BRPF3 (99% identical), dog BRPF3 (96% identical), pig BRPF3 (96% identical), rabbit BRPF3 (96% identical), guinea pig BRPF3 (93% identical), mouse Brpf3 (92% identical), rat Brpf3 (92% identical), macaque BRPF3 (89% identical), zebrafish brpf3b (62% identical), tropical clawed frog brpf3 (57% identical), zebrafish brpf3a (54% identical), Drosophila melanogaster Br140 (37% identical), and 2 more. Paralogues in human: BRD1 (53% identical), BRPF1 (50% identical), JADE3 (17% identical), JADE1 (17% identical), JADE2 (17% identical), MLLT10 (16% identical), MLLT6 (16% identical), PHF14 (15% identical).
Diseases named in the same sentence as BRPF3 in open-access papers:
BRPF3 is named in the same sentence as 6 diseases in open-access papers, as found by Europe PMC text mining. Sharing a sentence is not in itself a finding about the gene and the disease. The quoted sentences say what the papers report.
autism (1 paper, 2024). Persistent deficits in social interaction and communication and interaction as well as a markedly restricted repertoire of activity and interest as well as repetitive patterns of behavior. "Four Qualifying variants in B1 genes (with published indirect association with autism) were identified in four subjects, in the following genes: BRPF3, GTF2A1, POGLUT3, and TMEM184B, including a de novo loss-of-function variant in POGLUT3." (PMID 38256266, 2024).
cyst (1 paper, 2020). A sac-like closed membranous structure that may be empty or contain fluid or amorphous material. "We found that Brpf3 overexpression decreased the size of EBs and the cyst formation within EBs was abnormally delayed." (PMID 32555450, 2020).
renal clear cell carcinoma (1 paper, 2022). "Brpf3 was shown to be critical in renal clear cell carcinoma (KIRC)." (PMID 36077987, 2022).
tumor (2 papers, 2015 to 2021). "KAT2A, SP140 and BRD9 protein expression was higher in tumor tissues, and SMARCA2, BRPF3, KAT2B and EP300 protein expression was lower in the tumor tissues." (PMID 34149798, 2021).
cancer (1 paper, 2023). A tumor composed of atypical neoplastic, often pleomorphic cells that invade other tissues. "As for BRPF2 and BRPF3, little is known about their engagement in cancer development and progression, leaving an open question of whether they exert similar activity as BRPF1 in maintaining cancer stem cell-like phenotype." (PMID 36674511, 2023).
BRPF3 also shares sentences with these, for which no sentence is quoted: migraine (2 papers).